UBQLN2 (ubiquilin 2)
Diseases named in the same sentence as UBQLN2 in open-access papers (continued):
Sharing a sentence is not in itself a finding about the gene and the disease.
neurodegenerative disease (continued). "Further research is required to confirm these findings and evaluate downstream effects of UBQLN2 on SG formation and dynamics and how this relates to neurodegenerative disease." (PMID 40663766, 2025). "This review will detail the emerging consensus on how UBQLN2 protects against neurodegenerative disease and will provide insights into potential therapeutic approaches." (PMID 40663766, 2025). "Previous work also shows that UBQLN2 is capable of regulating proteins known to contribute to neurodegenerative diseases." (PMID 40663766, 2025). "Collectively, these results support the view that UBQLN2 contributes to multiple neurodegenerative diseases." (PMID 36609661, 2023). "In this study, we have performed a comprehensive proteomic analysis of multiple animal models of Ubqln2-driven neurodegenerative disease." (PMID 33277362, 2021). "Individual proteins were assessed for altered levels in all tested Ubqln2-mediated models of neurodegenerative disease." (PMID 33277362, 2021). "Of the mammalian ubiquilins, UBQLN1, UBQLN2 and UBQLN4 are expressed in the brain and are associated to varying degrees with neurodegenerative diseases characterized by protein misfolding, aggregation and mislocalization." (PMID 33431932, 2021). "We performed the first large-scale global proteomic analysis of Ubqln2-mediated neurodegenerative disease, employing multiple models to identify proteins that are under the control of UBQLN2." (PMID 33277362, 2021). "Our results further indicate that the compromised autophagy-lysosomal pathway plays a critical role in the pathogenesis of UBQLN2-related neurodegenerative diseases." (PMID 30409191, 2018). "To better understand the role of UBQLN2 and its relevance to neurodegenerative disease, we isolated its binding partners from mouse brain using immunoprecipitation and mass spectrometry." (PMID 27477512, 2016). "Recent studies have revealed the complexity of UBQLN2 biology and allow deeper understanding as to how UBQLN2 dysfunction may contribute to neurodegenerative disease." (PMID 40663766, 2025). "In the case of UBQLN2-mediated neurodegenerative disease, however, the answer is far less clear." (PMID 38472280, 2024). "As ALS is a neurodegenerative disease, we examined whether a reduction of UBQLN2 also increases MAP1B levels in neuronal cells." (PMID 35777956, 2022). "Based on these findings, the increase in TRIM32 and concomitant decrease in CXX1B may be sensitive early indicators of developing Ubqln2-dependent neurodegenerative disease." (PMID 33277362, 2021). "It was therefore suggested that ubiquilin 2 pathology may be a general pathomechanism in neurodegenerative diseases." (PMID 24086754, 2013). "Ubiquilin 2 exerts a regulatory role in proteostasis and thus it has been suggested that ubiquilin 2 pathology may be a common event in neurodegenerative diseases." (PMID 24086754, 2013). "It is currently unknown whether UBQLN2 is present in aggregates in other neurodegenerative diseases and a first study did not detect mutations in UBQLN2 in FTD." (PMID 23673820, 2013). "Restoring the UBQLN2-ILVBL/ALDH3A2 axis attenuates neurodegenerative phenotypes in neurons, organoids and mice, establishing UBQLN2 as a critical regulator of metabolic homeostasis in ALS/FTD and other related neurodegenerative diseases." (PMID 41912662, 2026). "Failed protein degradation is a hallmark of many neurodegenerative diseases, including ALS and FTD; however, it is not clear exactly how ALS/FTD-associated UBQLN2 mutations contribute to pathogenesis." (PMID 40663766, 2025). "However, the relationship between UBQLN2 LLPS and the development of neurodegenerative diseases, such as Parkinson’s disease (PD), remains unclear." (PMID 41087580, 2025).
neurodegenerative disease (continued). "Future analyses of the interactomes of wild-type and mutant SQSTM1, TBK1 and VCP are needed to pinpoint how these proteins cooperate in a common complex with OPTN and UBQLN2 and how alterations in this complex may lead to ALS or other neurodegenerative diseases." (PMID 27164932, 2016).
cancer (8 papers, 2016 to 2024). A tumor composed of atypical neoplastic, often pleomorphic cells that invade other tissues. "The heatmap indicated that UBQLN4 was positively related to UBQLN1 and UBQLN2 in most cancers with statistical significance, while few correlations were found between UBQLN4 and the remaining two members (UBQLN3 and UBQLNL)." (PMID 34539785, 2021). "Next, we were interested to see whether the phenotype we observed following the knockdown of either UBQLN1 or UBQLN2 is cancer specific." (PMID 37444499, 2023). "Recent studies have shown that UBQLN2 may promote cell proliferation and invasion in various types of cancer." (PMID 36644234, 2023). "Finally, it is worth mentioning that genes involved in ubiquitination processes and linked to cancer were among the significantly correlated genes (BAP1, RNF157, UBQLN2)." (PMID 37730697, 2023). "In addition to neurological diseases, UBQLN2 also plays an important role in malignant tumors." (PMID 36644234, 2023). "The role of UBQLN1 and UBQLN2 in regulating processes involved in cancer progression and tumorigenesis is still not completely understood." (PMID 37444499, 2023). "Furthermore, we also observed an increase in clonogenic potential following the loss of UBQLN1 and UBQLN2 in HPL1D cells, further confirming that the phenotype that we observed following the loss of UBQLN is not as cancer-specific." (PMID 37444499, 2023). "qRCR was used to determinate Ubqln2 expression in cancer and noncancerous tissues." (PMID 32293796, 2020).
neurological diseases (4 papers, 2023 to 2024). "This observed dysregulation of PEG10 in affected tissues of neurological disease, as well as the unique enrichment of UBQLN2 in neuromuscular tissues, further supports our hypothesis." (PMID 36951542, 2023).
tumor (3 papers, 2020 to 2023). "Concordantly, the Ubqln2 protein was closely associated with tumor size (P = .005), UICC stage (P = .012), and recurrence (P = .009)." (PMID 32293796, 2020). "IHC analysis showed that the expression of p38 MAPK and caspase-3 in the tumor tissues of the UBQLN2-KD + IR group was significantly higher than that in the WT + IR group." (PMID 36644234, 2023). "Multivariate analyses demonstrated that Ubqln2 expression level, UICC stage, vascular invasion status, resection potential, and tumor status were independent risk factors for OS in the TCGA cohort." (PMID 32293796, 2020). "Ubqln2 expression, histological grade, tumor size, intrahepatic metastasis status, and vascular invasion status were independent risk factors for OS in the IHC cohort." (PMID 32293796, 2020). "The expression of Ubqln2 was closely correlated with tumor size and UICC stage; thus, we examined the protein expression of Ubqln2 and Ki‐67 in eight samples of human HCC by IHC staining." (PMID 32293796, 2020). "The Ubqln2 mRNA level had significant relations with UICC tumor stage (P = .022), UICC stage (P = .034) and resection potential (P = .017)." (PMID 32293796, 2020). "In addition, the expression of Ki-67 in the tumor tissues of the UBQLN2-KD + IR group was obviously suppressed." (PMID 36644234, 2023). "Finally, the xenografted tumor experiment confirmed the radiosensitizing effect of silencing UBQLN2 on ESCC in vivo." (PMID 36644234, 2023). "Moreover, the expression level of Ubqln2 was intimately associated with tumor size and UICC stage in HCC patients at both the protein and mRNA levels, suggesting that Ubqln2 is a potential activator that promotes tumor growth." (PMID 32293796, 2020). "In summary, high Ubqln2 expression labels a group of HCC patients with aggressive disease, and Ubqln2 has close correlations with tumor size and UICC stage." (PMID 32293796, 2020). "Consistently, Ubqln2 protein expression level with other the clinical features (eg UICC stage, tumor size, intrahepatic metastasis status, vascular invasion status, and recurrence status) were also identified as risk factors contributing to OS in the IHC cohort." (PMID 32293796, 2020).
UBQLN2 also shares sentences with these, for which no sentence is quoted: Paget's disease of bone (2 papers); Pick disease (2); Adult onset (1); Becker muscular dystrophy (1); cognitive decline (1); colorectal cancer (1); distal hereditary motor neuropathies (1); frontotemporal dementia and parkinsonism (1); glioblastoma (1); hereditary spastic paraplegia (1); invasive carcinoma (1); motor neuron degeneration (1); mucolipidosis type IV (1); Myeloma (1); night blindness (1); Onset (1); Primary lateral sclerosis (1); progressive bulbar palsy (1); sarcoma (1); Spastic paraplegia (1); urothelial carcinoma (1); X-linked sideroblastic anemia with ataxia (1).